KLHL18 (kelch like family member 18)
Description:
Substrate-specific adapter of a BCR (BTB-CUL3-RBX1) E3 ubiquitin-protein ligase complex required for mitotic progression and cytokinesis. The BCR(KLHL18) E3 ubiquitin ligase complex mediates the ubiquitination of AURKA leading to its activation at the centrosome which is required for initiating mitotic entry. Regulates light-and dark-dependent alpha-transducin localization changes in rod photoreceptors through UNC119 ubiquitination and degradation (By similarity). Preferentially ubiquitinates the unphosphorylated form of UNC119 over the phosphorylated form (By similarity). In the presence of UNC119, under dark-adapted conditions alpha-transducin mislocalizes from the outer segment to the inner part of rod photoreceptors which leads to decreased photoreceptor damage caused by light (By similarity).
Synonyms: KIAA0795; FLJ13703
Tractability: Small molecule: it belongs to a druggable protein family. PROTAC: ubiquitination databases record sites on it; its protein half-life has been measured.
Gene: Protein-coding gene on chromosome 3 (47,282,633 to 47,346,816, forward strand). Ensembl gene ENSG00000114648.
Subcellular location (Human Protein Atlas): Nucleoplasm; Nuclear bodies
Gene Ontology:
Molecular function: protein binding; ubiquitin-like ligase-substrate adaptor activity
Biological process: positive regulation of mitotic cell cycle phase transition; protein ubiquitination; proteasome-mediated ubiquitin-dependent protein catabolic process
Cellular component: Cul3-RING ubiquitin ligase complex; cytoplasm
Genetic constraint (gnomAD): Loss-of-function variants: 38 observed, 59.9 expected, observed/expected ratio (o/e) 0.63, 90% interval 0.49 to 0.83. The upper end of that interval is the gene's LOEUF score, 0.83, which puts it in group 3 of 6, group 1 being the genes least tolerant of losing a copy. Missense variants: 623 observed, 799.27 expected, observed/expected ratio (o/e) 0.78, 90% interval 0.73 to 0.83. Synonymous variants: 303 observed, 313.86 expected, observed/expected ratio (o/e) 0.97, 90% interval 0.88 to 1.06.
Homologues: Orthologues: chimpanzee KLHL18 (99% identical), macaque KLHL18 (99% identical), mouse Klhl18 (98% identical), pig KLHL18 (98% identical), rat Klhl18 (98% identical), guinea pig KLHL18 (97% identical), dog KLHL18 (97% identical), tropical clawed frog klhl18 (89% identical), rabbit KLHL18 (84% identical), zebrafish klhl18 (81% identical), Drosophila melanogaster KLHL18 (53% identical), Caenorhabditis elegans kel-3 (44% identical). Paralogues in human: KLHL20 (38% identical), KLHL17 (38% identical), KLHL2 (37% identical), KLHL12 (37% identical), KLHL1 (36% identical), KLHL28 (36% identical), KLHL3 (36% identical), KLHL5 (35% identical), KEAP1 (34% identical), KLHL4 (34% identical), KLHL8 (31% identical), IPP (31% identical), and 42 more.
Diseases named in the same sentence as KLHL18 in open-access papers:
KLHL18 is named in the same sentence as 8 diseases in open-access papers, as found by Europe PMC text mining. Sharing a sentence is not in itself a finding about the gene and the disease. The quoted sentences say what the papers report.
breast carcinoma (2 papers, 2020 to 2024). "In this interaction, KLHL18 has a tumor suppressor function, while KDSR is active through sphingolipid metabolism and its inhibition causes endoplasmic reticulum dysfunction specific to breast cancer cells." (PMID 38627780, 2024). "KLHL18 expression was also correlated with a tumor suppressor function in various cancers such as breast cancer, supporting the hypothesis that KLHL18 acts as a tumor suppressor gene." (PMID 33292627, 2020). "One of the first interactions that emerged in breast cancer tissue compared to normal tissue was the interaction between RMND5A, EIF5B, SUN2, KLHL18, KDSR, RPSK6KA3 ceRNAs and the miR-338-5p, miR-223-3p, miR-129-5p, miR-642a-5p, miR-3619-5p, and miR-382-5p miRNAs." (PMID 38627780, 2024).
lung carcinoma (1 paper, 2020). "To determine the role of KLHL18 in lung cancer, we performed immunohistochemical analysis of 214 NSCLC samples." (PMID 33292627, 2020). "KLHL18 was highly expressed in the normal bronchial epithelial cell line HBE, whereas its expression was relatively low in the other six lung cancer cell lines." (PMID 33292627, 2020).
lymph node metastasis (1 paper, 2020). "KLHL18 expression was inversely correlated with lymph node metastasis (P < 0.0001), tumor size (P = 0.037), and TNM stage (P = 0.019)." (PMID 33292627, 2020).
non-small cell lung carcinoma (1 paper, 2020). A group of at least three distinct histological types of lung cancer, including non-small cell squamous cell carcinoma, adenocarcinoma, and large cell carcinoma. "The expression of Kelch-like protein 18 (KLHL18) in non-small cell lung cancer (NSCLC) is lower than that in normal lung tissue according to the Gene Expression Profiling Interactive Analysis database." (PMID 33292627, 2020).
tumor (3 papers, 2016 to 2024). "Based on this discovery, we suspect that KLHL18 affects PD-L1 function by preventing its binding to its specific recognition protein PD-1, thereby inducing immune cells to kill tumor cells." (PMID 33292627, 2020). "Our results identified the tumor-suppressive mechanism of KLHL18 and suggested that it is closely related to NSCLC occurrence and development." (PMID 33292627, 2020). "Therefore, we theorize that the KLHL18 protein can regulate the immune microenvironment of tumor cells, thereby demonstrating its function as a tumor suppressor." (PMID 33292627, 2020). "Although additional in vivo experiments are warranted to test whether KLHL18 protein affects the sensitivity of tumor cells to immunosuppressive drugs, our findings have important implications for understanding the role and mechanism of action of KLHL18 in tumorigenesis." (PMID 33292627, 2020). "Our data show that the expression of KLHL18 is decreased in NSCLC with a decreasing degree of differentiation and is correlated with TNM stage, lymph node metastasis, and tumor size." (PMID 33292627, 2020). "The MDR included the CCDC12, NBEAL2, SETD2, KIF9 and KLHL18 genes, of which SETD2 was the most significantly underexpressed in tumour cells." (PMID 27282254, 2016). "We found that the tumor-inhibitory effect of the KLHL18 protein was achieved by promoting the ubiquitination and degradation of phosphatidylinositol 3-kinase (PI3K) p85α and inhibiting the expression of PD-L1 protein, ultimately preventing tumor cell immune escape." (PMID 33292627, 2020).
cancer (1 paper, 2020). A tumor composed of atypical neoplastic, often pleomorphic cells that invade other tissues. "We found that KLHL18 is downregulated in cancer cells and is associated with poor prognosis." (PMID 33292627, 2020). "Next, we examined 22 pairs of NSCLC and adjacent tissues using quantitative polymerase chain reaction (qPCR) and found that the expression of KLHL18 in adjacent tissues was significantly higher than that in cancer tissues (*P < 0.05, **P < 0.01)." (PMID 33292627, 2020). "Based on these results, we selected NCI-A549 and NCI-H1299 cells, with relatively moderate expression of KLHL18, as representative cancer cell lines for an in-depth study of NSCLC." (PMID 33292627, 2020).
KLHL18 also shares sentences with these, for which no sentence is quoted: bladder tumors (1 paper); deafness (1).